CSTA (cystatin A)
Diseases named in the same sentence as CSTA in open-access papers (continued):
Sharing a sentence is not in itself a finding about the gene and the disease.
ductal carcinoma in situ (1 paper, 2015). "Later CSTA was also associated with the regulation of the progression of ductal carcinoma in situ to invasive BC." (PMID 25857299, 2015).
endometrial cancer (1 paper, 2023). Primary or metastatic malignant neoplasm involving the endometrium (mucous membrane that lines the endometrial cavity). "Based on this analysis, CSTA and S100A7 were confirmed to discriminate early-stage endometrial cancer from controls with AUC values of 0.75 (0.64–0.85) and 0.73 (0.63–0.83), respectively." (PMID 36807337, 2023). "A four-marker panel comprising CSTA, S100A7, MMP9 and SERPINA10 predicted endometrial cancer with an AUC of 0.84 (0.77–0.92), sensitivity of 72.2%, specificity of 87.8%, NPV of 86.7% and PPV of 74.1%." (PMID 36807337, 2023).
endometriosis (1 paper, 2024). The growth of functional endometrial tissue in anatomic sites outside the uterine body. "Moreover, cyto-hub gene analysis revealed that CSNK2A1, CSNK2A2, TOP1, PRKACA, RBM39 (plasma), ALB, ACTB, GAPDH, FN1, APOA1 (serum), S100-A9, CXCL1, IL1RN, CSTA, S100-A8 (menstrual blood) and THBS1, ALB, CD44, ANXA2, and LUM (urine) were the top 5 proteins expressed in women with endometriosis." (PMID 39061077, 2024).
esophagus tumors (1 paper, 2020). "Furthermore, lower mRNA levels of CSTA have been reported in breast, prostate, skin, and esophagus tumors as compared to adjacent control tissues." (PMID 32528874, 2020).
gastric cancer (1 paper, 2009). A primary or metastatic malignant neoplasm involving the stomach. "In CSTA a heterozygous mutation was detected in both GP202 and IPA220 gastric cancer cells transfected with UPF1 siRNA, at position 298 (mRNA seq." (PMID 19563644, 2009). "In addition we selected two genes potentially inactivated by nonsense mutation which were located outside deleted areas, but showed high log2 ratios and no known splice variants (CSTA for the GP202 and INHBB for the IPA220 gastric cancer cell lines)." (PMID 19563644, 2009).
infertile (1 paper, 2018). "Their results demonstrated 10 over-expressed proteins in the infertile group, including: Ubiquitin-conjugating enzyme E2C binding protein (UBE2C), Cystatin-A (CSTA), Dermcidin (DCD), Ceruloplasmin (CP), Ras GTPase-activating-like protein IQGAP1 (IQGAP1)." (PMID 29881623, 2018).
invasive breast carcinoma (1 paper, 2016). A carcinoma that infiltrates the breast parenchyma. "Loss of CSTA expression is associated with progression of ductal breast cancer in situ to invasive breast cancer, presumptively via increased cathepsin B activity which raises the possibility that cathepsin B may be a relevant therapeutic target in aGCT." (PMID 26893359, 2016).
lung disease (1 paper, 2025). "Cathepsin B and Cystatin A expression at PAJs are thus a therapeutic vulnerability that could be exploited to prevent or even cure lung disease." (PMID 39747171, 2025).
metabolic syndrome (1 paper, 2019). A cluster of metabolic risk factors for CARDIOVASCULAR DISEASES and TYPE 2 DIABETES MELLITUS. "Then, we hypothesized that rat platelet CSTA/StfA content might be associated with some features of the metabolic syndrome." (PMID 31270351, 2019).
Obesity (1 paper, 2019). Accumulation of substantial excess body fat. "Significantly higher serum CSTA concentrations were found in patients with obesity or T2DM than in controls (p < 0.001 and p < 0.0001, respectively)." (PMID 31270351, 2019). "Twelve months after BS, serum CSTA levels were markedly decreased (1.64 ± 0.17 vs. 3.47 ± 0.36 ng/mL at baseline, p < 0.0001), strongly suggesting that CSTA platelet levels increase during obesity and are further stimulated by T2DM." (PMID 31270351, 2019).
ovarian carcinoma (1 paper, 2023). A malignant neoplasm originating from the surface ovarian epithelium. "Based on the data presented here, the combination of untargeted (MALDI-TOF MS protein profiling) and targeted (FLOWER) detection methods provides a powerful platform that has led to the detection of cystatin A, a promising candidate ovarian cancer biomarker." (PMID 37301378, 2023). "The dataset was then queried for the presence of cystatin A. In the tampon extracts, cystatin A in samples diagnosed with ovarian cancer displayed an overall two-fold increase compared with samples diagnosed as benign when comparing the mean intensities as measured by MALDI-TOF MS." (PMID 37301378, 2023). "Furthermore, not all ovarian cancer samples displayed elevated levels of cystatin A (i.e., TP42); similarly, cystatin A levels in benign samples were also variable." (PMID 37301378, 2023).
papilloma (1 paper, 2015). A benign epithelial neoplasm that projects above the surrounding epithelial surface and consists of villous or arborescent outgrowths of fibrovascular stroma. "Upregulation of CSTA is also detected in another transgenic mouse model overexpressing the early gene region of the human papillomavirus type 8, these mice develop papillomas similar to our Inv-Dsg2 mice." (PMID 25785582, 2015).
pemphigus (1 paper, 2015). Pemphigus is a group of rare autoimmune diseases that cause blistering of the skin and mucous membranes (mouth, nose, throat, eyes, and genitals).This conditioncan occur at any age, but often strikes people in middle or older age. "It would be interesting to assess the expression of CSTA in pemphigus patients’ skin." (PMID 25785582, 2015).
sarcoma (1 paper, 2015). A usually aggressive malignant neoplasm of the soft tissue or bone. "Overexpression of CSTA has been detected in a variety of human cancers including lung, breast, head and neck, vulva, cervix, esophagus and prostate, and in some mouse sarcomas." (PMID 25785582, 2015).
skin cancer (1 paper, 2015). "Furthermore, CSTA inhibits cathepsins, which are also deregulated in skin cancer." (PMID 25785582, 2015).
tumor (30 papers, 2006 to 2025). "High extracellular CSTA levels in colorectal carcinoma are linked to shorter survival time, indicating their involvement in tumor growth." (PMID 40007784, 2025). "Cystatin A was positively expressed in 62.3% (71/114) of tumor tissues, and expression was associated with age (P = 0.009), but not with sex, pathologic type, or stage (P > 0.05)." (PMID 26634210, 2015). "Upregulation of cystatin A in tumor tissues can reversely balance the overexpression of tumor-associated proteolytic enzyme activity in a certain range." (PMID 25396333, 2014). "One of the genes found elevated in all mutants and not elevated in the wild-type was CSTA, which encodes for the cysteine protease inhibitor cystatin A. This gene is present in most tissues, its expression is associated with tumor growth and it is a serum biomarker for screening cancer patients." (PMID 22615763, 2012). "Moreover, high expression of CSTA was inversely associated with tumor grade (p<0.01)." (PMID 29581829, 2018). "The expressions of NEU1 and CSTA were significantly increased in tumor tissues compared with those in the resection margins." (PMID 40141206, 2025). "In this regard, CSTA expression has been observed in several tumor tissues, and it has been recognized as having diagnostic significance." (PMID 39792573, 2025). "The molecular mechanisms through which CSTA exerts tumor-suppressing or oncogenic effects remain poorly understood, even though most studies have emphasized the correlation between CSTA expression levels and clinical outcomes only." (PMID 40007784, 2025). "Next, we used DNA microarray gene expression profile analysis to examine how tumor tissues were affected in the murine SC PDAC model of Retro‐PAN02‐CSTA by the induced expression of CSTA." (PMID 39792573, 2025). "High levels of CSTA have been correlated with tumor progression and, in this regard, CSTA suppresses tumor invasion in various types of cancer." (PMID 39792573, 2025). "Taken together, we confirmed that CSTA induced a very distinct anticancer immunity environment in PDAC tumor by enhancing activity and recruitment." (PMID 39792573, 2025). "In the present study, we produced murine PDAC tumor cell lines able to continuously overexpress CSTA or to express CSTA upon selective induction." (PMID 39792573, 2025). "The identified pathway maps related to gene set B were associated with downregulated regulation of the cell cycle, checkpoint, and apoptosis in the presence of CSTA within the tumor tissues, confirming a diminished proliferation of cancer cells." (PMID 39792573, 2025). "Overexpression of CSTA gene inhibits tumor cell growth, migration and invasion through regulating the MAPK and AKT pathways." (PMID 39140365, 2024). "By focusing on crucial sphingolipid genes like SMPD2 and CSTA, the efficacy of anti-tumor therapy can be increased in HCC cells." (PMID 37006285, 2023). "The study by Ma and colleagues concluded that cystatin A exerts a tumour suppressive effect by inhibiting MAPK and AKT pathways." (PMID 36807337, 2023). "The tumor tissues derived from basal, Her2, LumA, and LumB breast tissues were not significantly different between normal and tumor ones; for CSTA: the expression levels are displayed in the box plot." (PMID 34572798, 2021). "Previous studies demonstrated that higher levels of CSTA in tumor tissues have been shown to correlate with a favorable prognosis of patients with HNSCC, that was consistent with our finding of survival analysis." (PMID 32528874, 2020). "CSTA, one of the tumor suppressors, had the anti-apoptotic effect and maintaining cell-cell adhesion." (PMID 33133157, 2020). "In our study, CSTA was down-regulated in tumor tissues compared with normal tissues, showing a significant correlation with HNSCC." (PMID 32528874, 2020). "Taken together, CSTA overexpression inhibits tumor cell growth, migration and invasion through modulating the MAPK and AKT pathways." (PMID 29581829, 2018).
tumor (continued). "CSTA along with other cystatins merits further investigation based on their impact on various aspects of tumor biology and their potential in cancer treatment." (PMID 29581829, 2018). "Both MIP-3α and cystatin A overexpressions in NPC tumor tissues were strong independent factors of poor prognosis in NPC patients." (PMID 26634210, 2015). "Furthermore, depending on tumor type, CSTA appears to modulate both antitumor and protumor responses." (PMID 39792573, 2025). "This could lead to increased tumor invasion and metastasis during cancer progression, as the mutant CSTA is less effective in inhibiting its enzymatic functions." (PMID 40007784, 2025). "Furthermore, CSTA is recognized for its ability to inhibit cathepsin B (CTSB), a cysteine protease implicated in the degradation of the extracellular matrix and tumor growth." (PMID 40007784, 2025). "CST6, TRIM29, and CSTA (an ER target gene) possessed tumor-suppressive actions toward BC." (PMID 37370814, 2023). "Furthermore, the protein levels of the CSTA gene was significantly lower in tumor tissues compared with normal tissues based on the HPA database." (PMID 32528874, 2020). "Indeed, the inhibitory effects of CSTA in tumor motility are in good agreement with its role in MET, since EMT is believed to be associated with tumor invasion and metastasis." (PMID 29581829, 2018). "It is believed that CSTA regulates cellular proliferation, tumor growth and metastasis." (PMID 22615763, 2012). "On the other hand, the genes downregulated in tumor tissue expressing CSTA (upregulated in tumor tissue without CSTA) were related to pathways associated with regulation of the cell cycle, checkpoint, and apoptosis, suggesting an overall reduced proliferation activity of cancer cells." (PMID 39792573, 2025). "Moreover, CSTA altered the gene expression profile in DNA microarray of tumor tissues." (PMID 39792573, 2025). "Notably, ectopic overexpression of Cystatin A rescued tumor cells from TNF-induced apoptosis." (PMID 25648368, 2015). "Cystatin A (CSTA), also known as stefin A, functions as an inhibitor of cysteine proteases and is recognized as a tumor suppressor." (PMID 41325308, 2025). "Mechanistic findings indicate that the overexpression of CSTA in squamous cell carcinoma (OSCC) inhibits epithelial-to-mesenchymal transition (EMT), hence reducing the migration and invasion of tumor cells." (PMID 40007784, 2025). "Other mechanistically different cysteine protease inhibitors of various efficacy; including cystatin A, cystatin B62, SERPINB163, SERPINB664, and SERPINB1365, were detected by quantitative RT-PCR in both tumor cell lines." (PMID 35022507, 2022). "Other signature genes (TP63, CERS3, CSTA, CLCA2, DSC3 and DSG3) upregulated in C1 tumours are also markers of the squamous-like subtype, while further columnar-like marker genes (MUC5B and RGL3) are upregulated in C2 tumours." (PMID 36207323, 2022). "Mac_2 expressed Cathepsin genes (e.g., CSTA, CSTD) in a tumor-specific manner, which are important for ECM remodeling." (PMID 34921160, 2021). "Cystatin A, a protein that interacts with SLC12A8, is a putative tumor suppressor that modulates extracellular matrix remodeling, cell adhesion, tumor invasion, and metastasis." (PMID 34365894, 2021). "We further analyzed the relationship between CSTA expression and tumor grade in SCC subtype and found that higher CSTA expression was significantly correlated with lower grade (p=0.031)." (PMID 29581829, 2018). "Thus, whether CSTA is an oncogene or a tumor suppressor is unresolved." (PMID 25785582, 2015). "The strong staining of cystatin A, involucrin and SPRR3 was predominantly localized in the hyperkeratotic portion of tumor nests in well-differentiated ESCC tissues, but there was weak or negative staining in moderately- or poorly-differentiated ESCC tissues." (PMID 24796531, 2014).
tumor (continued). "Then, we examined the gene expression of cytokines related to anticancer immunity in tumor tissues from PDAC tumors that were expressing or not expressing CSTA." (PMID 39792573, 2025). "By focusing on crucial sphingolipid genes, such as SMPD2 and CSTA, the sensitivity of HCC to anti-tumor therapy may be enhanced." (PMID 37006285, 2023). "The genes upregulated in tumor tissue expressing CSTA (downregulated in tumor tissue without CSTA) were related to pathways associated with the antitumor immune response: mainly IFN‐γ and IFN‐α/β regulation for activation of macrophages and DCs, but also enhanced antigen presentation activity." (PMID 39792573, 2025). "The continuous overexpression of CSTA in PAN02‐CSTA‐GFP PDAC models ultimately led to such a reduction in tumor size that we could not sample sufficient amounts of tissues for a detailed investigation of the CSTA mechanism." (PMID 39792573, 2025). "Precisely, 1684 genes were upregulated in tumor tissue by CSTA (downregulated in tumor tissue without CSTA; gene set A) and 771 genes were downregulated in tumor tissue by CSTA (upregulated in tumor tissue without CSTA; gene set B)." (PMID 39792573, 2025).
cancer (27 papers, 2009 to 2025). A tumor composed of atypical neoplastic, often pleomorphic cells that invade other tissues. "The presence of the CSTA variants in cancer patients provides additional support to these findings of the Y43C and E94K polymorphisms having detrimental effects on the protein function." (PMID 40007784, 2025). "Among them, CISD1 was also found to be closely linked to CLEC12B, CLEC2B and CSTA in a variety of cancers, with CLEC2B being involved in the largest number of cancer types." (PMID 36030279, 2022). "Higher levels of cystatin A in body fluids have been associated with a poor prognosis in cancer patients." (PMID 26634210, 2015). "Although evidence supports a causal role for proteases in malignant progression of human cancers, the role of CSTA is somewhat complicated and controversial." (PMID 25785582, 2015). "The specific function of CSTA in cancer progression, particularly the impact of different amino acid alterations on cystatin-cathepsin interactions, is still not fully elucidated." (PMID 40007784, 2025). "Simultaneously, due to the clinical significance of the CSTA-CTSB interaction in various cancers, CTSB was selected for protein-protein docking and molecular dynamics simulation." (PMID 40007784, 2025). "The relationship between CSTA and cathepsins illustrates the balance between the two, with disruptions in their interaction playing a role in cancer progression." (PMID 40007784, 2025). "TP63 was identified as a differentially expressed gene (DEG) in cancer cell lines that acquired gefitinib resistance, and CSTA is one of the top 10 hub genes in a network of DEGs for gefitinib resistant cancer cell line." (PMID 35584089, 2022). "Cathepsins are lysosomal cysteine proteases, and their aberrant expression is related to the malignancy of tumors, and thus, the inhibition of cathepsins by CSTA expression has been considered to be a target for cancer treatment." (PMID 35976950, 2022). "After investigating the pan-cancer section of ENCORI, an online tool, CISD1 was discovered to be highly linked to CLEC2B, CLEC12B and CSTA in a variety of cancer types." (PMID 36030279, 2022). "The inhibition of CTSD activity is one of the targets for cancer treatment by controlling the expression of CSTA." (PMID 35976950, 2022). "Immunohistochemical analysis of NPC tissues revealed that MIP-3α and cystatin A were predominantly expressed in the cytoplasm of cells in the cancer nests, and CCR6 was expressed in the cell membrane." (PMID 26634210, 2015). "In this report we showed that ectopic expression of Dsg2 in the murine epidermis dramatically altered the expression of many genes involved in cell cycle regulation and cancer development, including the expression of the cysteine protease inhibitor, CSTA." (PMID 25785582, 2015). "Notably, multiple studies have demonstrated that CSTA expression correlates with improved prognosis in cancer." (PMID 41325308, 2025). "Diagnoses for samples with the same primary cancer were not uniform, which may have affected the variable amounts of cystatin A present in said samples despite being diagnosed with the same primary cancer." (PMID 37301378, 2023). "In accordance with the loss of CSTA in all of the SCC cell lines that we investigated, we found that CSTA was lowly expressed in lung SCC with higher grade, reflecting the fact that cancer cell lines are usually derived from primary tumors with poor differentiation and/or advanced stage." (PMID 29581829, 2018). "Cystatin A (CSTA), a cysteine protease inhibitor, is a key precursor protein that constitutes the cornified cell envelope of keratinocytes and has been proven to play an important role in epidermal development as well as invasion and metastasis of various cancers." (PMID 37547246, 2023).
cancer (continued). "Therefore, cystatin A requires detection in many more samples for validation; however, it has the potential to be multiplexed with other biomarkers and forms the basis of investigating vaginal microproteins in cancer progression." (PMID 37301378, 2023). "In invasive ductal breast carcinoma, the cancer cell expression of the protease inhibitor, CSTA and genes involved in adhesion, FAT1, DST, and TMEM45A, were shown to be involved in cancer invasiveness." (PMID 36114508, 2022). "We observed bimodal gene expression in columnar-like and squamous-like cancers, including MUC5B, KRT5 and CSTA, that differentiates ADC from SCC." (PMID 33462395, 2021). "Under the differentially expressed genes we identified several genes previously related to cancer including the up-regulated SSX1, SSX2, RXFP2, RYR2 and the down-regulated CSTA, TSPAN7, NEO1, S100A, SERPINB5 and SEPP1." (PMID 25857299, 2015). "cystatin A, involucrin and SPRR3 expression was significantly higher in carcinoma with well differentiation than that with moderate or poor differentiation (P = 0.002, P = 0.003 and P = 0.010, respectively)." (PMID 24796531, 2014). "The functional role of Cystatin A in these cancers has not been completely elucidated." (PMID 19838297, 2009).